SV2A (synaptic vesicle glycoprotein 2A)
Diseases named in the same sentence as SV2A in open-access papers (continued):
Sharing a sentence is not in itself a finding about the gene and the disease.
depression (13 papers, 2019 to 2025). "Greater symptoms of depression are associated with reduced radioligand binding to SV2A in the dorsolateral prefrontal cortex, anterior cingulate cortex, and hippocampal regions." (PMID 37252156, 2023). "PET studies on several neuropsychiatric disorders linked to synaptic dysfunction, including depression, have found lower cerebral SV2A density in patients compared to healthy individuals." (PMID 37814129, 2023). "Finally, grey matter loss, cortical thinning and lower SV2A levels have been found in other neuropsychiatric disorders, such as major depression, substance use disorders, post-traumatic stress disorder, and others." (PMID 36056106, 2023). "Meanwhile, the positive associations with the SV2A receptor in MDD subtype 1 contrast with established findings that demonstrated an inverse correlation between the severity of depression and SV2A density." (PMID 41171150, 2025). "In the studies reviewed herein, psilocybin increased SV2A under basal conditions in pigs, whereas ketamine increased SV2A only among humans with depression/PTSD who had low baseline SV2A expression in the hippocampus and PFC." (PMID 37435405, 2023). "The hippocampus is often the target of research on neuroplasticity as it is a key region in learning and memory, and patients with severe depression have been found to have lower SV2A in the hippocampus and several neocortical regions." (PMID 37814129, 2023). "The severity of depressive symptoms was inversely correlated with SV2A density, and individuals with high levels of depression showing lower SV2A density compared to healthy controls (n = 21)." (PMID 30948709, 2019). "Here, the authors use positron emission tomography (PET) to measure levels of the synaptic marker SV2A and show that SV2A density is lower in those with more severe symptoms of depression." (PMID 30948709, 2019). "Three PET studies have been performed investigating SV2A in major depressive disorder (MDD)." (PMID 39134769, 2024). "Furthermore, the severity of depression is inversely correlated with neuronal SV2A density and reduced GABAergic inhibitory neurotransmission." (PMID 37252156, 2023). "The authors also completed a post hoc study, showing that patients with lower SV2A density at baseline may exhibit an increased SV2A density 24 h after ketamine administration, coherent with the reduction in severity of depression." (PMID 35573314, 2022).
Cognitive impairment (12 papers, 2019 to 2025). Abnormal cognition is characterized by deficits in thinking, reasoning, or remembering. "Since SV2A was closely associated with cognitive impairment in patients with AD, the early diagnostic and differential diagnostic ability of SV2A for AD was also analyzed." (PMID 38615037, 2024). "All these results suggest that, in the hippocampal area, the deletion of the SV2A gene in one (cHZ mice) or in both alleles (cKO mice) involves statistically significant changes in cognition, including a cognitive impairment and anxiety-related problems, usually present in the epileptic disease." (PMID 31166988, 2019). "SDI-118 is a small molecule which modulates the activity of synaptic vesicle glycoprotein 2A (SV2A) in the brain and shows cognitive enhancing effects in a range of animal models of cognitive deficit." (PMID 36733374, 2022). "This last hypothesis is supported by a PET study in mild cognitive impairment and AD, which reported a strong positive correlation between hippocampal amyloid-β deposition and increased SV2A density." (PMID 38173031, 2024). "There may be a connection with the mechanisms of action of levetiracetam since several studies using SV2A PET tracers show reduction in SV2A expression associated with several neuropsychiatric and neurodegenerative diseases that are associated with cognitive deficits." (PMID 33177974, 2020). "However, the possible implication of SV2A in the cognitive impairment and mood disorders accompanying epileptic disease is still unknown." (PMID 31166988, 2019). "Treatments targeting synaptic dysfunction via synaptic vesicle glycoprotein 2A (SV2A) modulators such as ABBV-552 and AGB101, are in the phase I–III clinical trials for AD and for mild cognitive impairment (MCI) due to AD." (PMID 40993829, 2025).
temporal lobe epilepsy (10 papers, 2011 to 2024). A localization-related (focal) form of epilepsy characterized by recurrent seizures that arise from foci within the temporal lobe, most commonly from its mesial aspect. "On the other hand, pilocarpine-induced seizures– a well-validated model of temporal lobe epilepsy– lead to overexpression of SV2A, which can be normalized by brivaracetam." (PMID 38776036, 2024). "The reduction of SV2A expression in temporal lobe epilepsy was seen also in a study of [11C]UCB-J PET in epileptic patients." (PMID 35573314, 2022). "In resected tissue from temporal lobe epilepsy patients, a 40 percent reduction in SV2A levels were observed in the neocortex by immunoblot." (PMID 34435329, 2021). "Alterations in SV2A abundances have been a topic of interest in the context of temporal lobe epilepsy." (PMID 34435329, 2021). "In this paper, we performed the first in vivo longitudinal study of variations in SV2A expression in the kainic acid (KA) rat model of temporal lobe epilepsy (TLE)." (PMID 32206990, 2020). "The main purpose of this study was to understand how the positron emission tomography (PET) measure of the synaptic vesicle 2A (SV2A) protein varies in vivo during the development of temporal lobe epilepsy (TLE) in the kainic acid rat model." (PMID 32206990, 2020). "The hippocampus is already well-known to be a generator of temporal-lobe epilepsy (TLE), a form found in humans associated with a down-regulation of SV2A expression." (PMID 27861538, 2016). "SV2A has been identified as a target of the antiepileptic drug, levetiracetam, and has recently been found in patients with temporal lobe epilepsy." (PMID 23550224, 2013). "In contrast, qualitative analyses of expression reveal decreased SV2A expression in temporal lobe epilepsy." (PMID 22220214, 2011). "Thus, chronic administration of brivaracetam ameliorated the over-expression of SV2A and the synaptic dysfunction in the pilocarpine model of temporal lobe epilepsy in rats." (PMID 38776036, 2024). "Thus, [18F]UCB-H PET detected SV2A variations in specific cases of kainic acid-induced temporal lobe epilepsy during the distinct phases of the pathological progression (early, late, transition and chronic)." (PMID 35573314, 2022). "A decreased SV2A expression was also found in rodent models of temporal lobe epilepsy (TLE), further supporting the hypothesis that SV2A deficiency may contribute to epileptogenic progression and seizure initiation." (PMID 35686059, 2022).
dementia (9 papers, 2021 to 2025). Loss of intellectual abilities interfering with an individual's social and occupational functions. "Serum SV2A demonstrated significant efficacy in the differential diagnosis of AD from other dementias." (PMID 38615037, 2024). "In this study, SV2A levels in serum and CSF at different stages of AD and other types of dementia were analyzed using single-molecule array (Simoa) technology." (PMID 38615037, 2024). "Average group images of DVR demonstrated visible reduction and deposition of SV2A and Aβ binding, respectively, in both aMCI and dementia groups, compared to the CN group." (PMID 33402201, 2021). "First, the mean levels of CSF and serum SV2A in AD were the lowest in the three dementias." (PMID 38615037, 2024). "Lastly, we investigated whether cortical synaptophysin and SV2A density correlated with clinical measures, including disease duration, motor-to-dementia interval and CDR scores." (PMID 38173031, 2024). "A longer motor-to-dementia interval correlated with cortical SV2A loss in PDD cases (r = -0.32, p < 0.001), but not with cortical synaptophysin loss (p > 0.05)." (PMID 38173031, 2024). "The results showed that SV2A levels in the CSF gradually decreased with the severity of dementia." (PMID 38615037, 2024). "We aimed to answer these questions by examining whether blood-based levels of VAMP2 and SNAP25 along with blood-based ATN(I) biomarkers are associated with SV2A PET in the brains of older adults without dementia." (PMID 40620474, 2025). "The prefrontal, PCC/precuneus, and lateral occipital cortices also demonstrated significant reductions in SV2A binding in the dementia group, while non-significant trends of SV2A reduction were observed in aMCI participants (as compared to the CN group)." (PMID 33402201, 2021). "Finally, preliminary analysis of SV2A in the human brain postmortem suggested lower SV2A in HD gene carriers than in controls without dementia." (PMID 34531262, 2022).
Anxiety (8 papers, 2019 to 2026). Intense feelings of nervousness, tension, or panic often arise in response to interpersonal stresses. "It has been demonstrated that a decrease in SV2A expression in the mouse hippocampus is associated with an increase in anxiety and spatial memory deficits." (PMID 38182968, 2024). "BRV selectively binds to SV2A and an increase in anxiety and spatial memory deficits is associated with a hippocampal decrease in SV2A expression." (PMID 38182968, 2024). "Another clinical paper showed that among persons with stress-related mood and anxiety disorders, SV2A expression in the dlPFC was negatively associated with measures of worry and tension/anxiety." (PMID 37435405, 2023). "We confirmed that SV2A is associated with neuroticism or anxiety using an original GWAS of a community cohort (N = 1,706), and cross-referencing a published GWAS of multiple cohorts (Ns ranging from 340,569 to 390,278)." (PMID 32839459, 2020). "Of the sixteen sets we found, we focused our cell culture experimental work on the SV2A gene, based on its translational potential from prior known associations with anxiety, anxiety disorders, and with epilepsy." (PMID 32839459, 2020). "The association between SV2A and anxiety, however, is strengthened by leveraging available original and published GWAS data from large-scale samples." (PMID 32839459, 2020). "The Elevated Plus Maze reveals that conditional knockout mice with decreased SV2A in the hippocampus have elevated anxiety levels." (PMID 36979479, 2023). "Conditional knockout mice with decreased SV2A in hippocampus are free of epileptic seizures but show elevated levels of anxiety, as measured with the Elevated Plus Maze59." (PMID 32839459, 2020). "Specifically, reduced levels of synaptic proteins, as measured by positron emission tomography (PET) detection of synaptic vesicle glycoprotein 2 A (SV2A), have been correlated to cognitive dysfunction, especially in working memory and executive function, as well as, to mood and anxiety symptoms." (PMID 41258376, 2026). "SV2A is expressed in various GABAergic inhibitory neurons and involves anxiety." (PMID 36979479, 2023). "Further studies are required to better understand the implication of SV2A in the sexual differences observed in anxiety, since it could have an impact in the choice of the treatment, depending on the sex." (PMID 31166988, 2019). "In particular, the phenotyping of the male heterozygous SV2A (+/-) mice revealed no motor differences but rather anxiety-like features in these mice compared with the wild type." (PMID 31166988, 2019).
Seizure (6 papers, 2013 to 2025). A seizure is an intermittent abnormality of nervous system physiology characterized by a transient occurrence of signs and/or symptoms due to abnormal excessive or synchronous neuronal activity in the brain. "In this context, it can be speculated that levetiracetam could potentially increase the SV2A activity, whatever this activity is and consequently, thereby decreasing epileptic seizures." (PMID 23937191, 2013). "Nevertheless, both LEV and BRV had significant effects on the lithium-pilocarpine-induced seizure model, which was in line with previous observations regarding LEV’s effect on this model and the common SV2A mechanism of both medications in this model." (PMID 33916190, 2021). "Seizure protection by LEV and other SV2A ligands strongly correlates with the degree of SV2A occupancy in vivo." (PMID 33826008, 2021).
memory impairment (5 papers, 2015 to 2025). "BRV functions by mitigating glutamate-induced excitotoxicity via its association with SV2A, and animal models have shown its ability to reverse memory impairment." (PMID 38999445, 2024). "Positron emission tomography of synaptic vesicle glycoprotein 2A has revealed a widespread synaptic loss in the brains of AD patients, demonstrating that alteration of the LTP mechanism is associated with memory impairment." (PMID 37795181, 2023). "Reductions in SV2A abundance and immunoreactivity occurred concomitantly with motor dysfunction and spatial learning and memory impairments in the 2 weeks post-injury." (PMID 34435329, 2021). "As noted, two previous studies in J20 and APP/PS1 mice have shown clear benefits of levetiracetam in reversing memory impairments in this model, suggesting that targeting SV2A alleviates AD symptoms across AD models." (PMID 25945128, 2015).
tauopathies (5 papers, 2021 to 2025). "Recent approaches that have investigated the role of synaptic loss in PSP and CBD aimed to better understand tauopathies by mapping synaptic density based on the affinity for a presynaptic vesicle glycoprotein (SV2A)." (PMID 38132096, 2023). "Additionally, exploring the impact of the levetiracetam/SV2A pathway on other tauopathy models and its long-term effects on cognitive function and neuroprotection will be crucial." (PMID 39767797, 2024). "Emerging synaptic targets: Synaptic loss assessed by PET using synaptic vesicle proteins 2A (SV2A) tracer [11C]UCB-J was recently reported in patients with primary tauopathies and in AD where a link between tau [assessed by [18F]flortaucipir] and SV2A was detected." (PMID 35082657, 2021). "Sufficiently specific PET tracers for alpha-synuclein co-pathology are lacking, tracers such as [18F]flortaucipir bind well to 3R/4R but do not bind equally well to other tauopathies, and SV2A-PET assessment needs to be further validated." (PMID 41340156, 2025).
Brain atrophy (4 papers, 2021 to 2025). Partial or complete wasting (loss) of brain tissue that was once present. "Structural MRI reflects that AD can lead to significant brain atrophy and studies also reported significantly reduced SV2A levels in many brain regions." (PMID 40163154, 2025). "There were no significant group differences between the groups in MRI measures of brain atrophy or PET uptake values for tracers targeted toward TSPO (marker of neuroinflammation), SV2A (marker of synaptic density), and fluorodeoxyglucose (marker of glucose metabolism) in 15-month-old female rats." (PMID 40359012, 2025).
generalized epilepsy (4 papers, 2011 to 2024). Epilepsy that is characterized by generalized seizure types and may have typical interictal and/or ictal EEG findings that accompany generalized seizure types (for example generalized spike-wave). "Levetiracetam is a broad spectrum AED used to treat focal and generalized epilepsy and has a unique mechanism of action involving binding to SV2A vesicles, which are widely distributed among synapses." (PMID 27808418, 2017). "Consequently, SV2A is a very attractive candidate gene for analysis in the context of both mono- and polygenic generalized epilepsies in humans." (PMID 22046416, 2011).
glioma (4 papers, 2013 to 2026). A benign or malignant brain and spinal cord tumor that arises from glial cells (astrocytes, oligodendrocytes, ependymal cells). "More recently, it has been demonstrated that levetiracetam controls more efficiently epileptic seizures when SV2A is highly expressed in tissue surrounding resected glioma." (PMID 23937191, 2013). "However, a clinical study has reported a better outcome in patients with higher SV2A expression in glioma tissues." (PMID 32667033, 2020).
neuroblastoma (4 papers, 2020 to 2023). Neuroblastoma (NB) is the most common solid, extracranial childhood tumor. "A study on neuroblastoma cells has shown that miR-133a and miR-218 target synaptic vesicle glycoprotein 2A (SV2A) at both the mRNA and protein levels." (PMID 36979479, 2023). "Earlier studies on NETs and neuroblastoma reported that the higher molecular weight isoform of SV2A was presented in the cytoplasm." (PMID 34884893, 2021). "In human neuroblastoma cells, transfection with miR-133a and miR-218 reduced both endogenous SV2A mRNA and protein levels, confirming miRNA targeting of the SV2A gene." (PMID 32839459, 2020). "Given that luciferase assays revealed an interaction between the SV2A 3′UTR on the one hand, and miR-133a and miR-218 on the other, we subsequently investigated the effects of miRNA transfection on SV2A mRNA and protein levels in human neuroblastoma SH-SY5Y cells." (PMID 32839459, 2020).
psychosis (4 papers, 2023 to 2026). "Our study shows that such synaptic losses can be detected at a macroscopic scale via autoradiography in rodents, and suggest that inhibitory interneuron dysfunction may be underlying the reductions of SV2A observed in patients with psychosis." (PMID 36573631, 2023). "There is evidence for the modulation of synaptic plasticity with pharmacologic, neurostimulation and behavioral treatments, however, synaptogenesis promoting interventions specifically targeting SV2A have yet to be established and could represent innovative treatment strategies for psychosis." (PMID 38898401, 2024). "Five studies (k = 5) met inclusion criteria, comprising n = 128 adults (psychotic disorder; n = 61 and healthy volunteers; n = 67 and specifically measuring synaptic density via positron emission tomography (PET) imaging of the synaptic vesicle glycoprotein 2 A (SV2A)." (PMID 38898401, 2024). "Although we found that SV2A did not reside within 5 kb of the CpG sites comprising the darkgreen module, our study does reinforce that methylomic alterations in synaptic genes are observed in AD+P, so this treatment could still be explored for its therapeutic efficacy in psychosis in AD." (PMID 39936280, 2025).
rhabdomyolysis (4 papers, 2024 to 2025). Necrosis or disintegration of skeletal muscle often followed by myoglobinuria. "Levetiracetam-induced rhabdomyolysis appears to occur in susceptible individuals, potentially due to increased sensitivity to SV2A activity in motor neurons." (PMID 41141152, 2025). "LEV may cause rhabdomyolysis through an unidentified mechanism mediated by SV2A." (PMID 40255845, 2025). "One theory suggests that levetiracetam may interact with SV2A in the motor nerve terminals of slow muscle fibers, leading to increased cholinergic neurotransmission and subsequent muscle stress, ultimately contributing to rhabdomyolysis." (PMID 39712784, 2024).
amyloid (3 papers, 2024 to 2026). "Further investigation into the underlying mechanisms revealed that SV2A, as a binding protein of APP, could reduce amyloidosis of APP by inhibiting the binding of BACE1 to APP and regulating the intracellular distribution of APP." (PMID 41521688, 2026).
prostate carcinoma (3 papers, 2021 to 2023). A carcinoma that arises from epithelial cells of the prostate gland. "Some promising results have been obtained through synaptic vesicle glycoprotein (SV2A) expression in PET imaging for neuroendocrine differentiation in prostate cancer." (PMID 37958702, 2023). "To validate these results, we analyzed SV2A expression in human prostate cancer tumor samples by immunohistochemistry." (PMID 33737929, 2021). "According to this hypothesis, it has been shown that the botulinum toxin type A (BTA), which molecularly binds to SV2A, can inhibit the growth of SV2A-expressing LNCaP prostate cancer cells, both in vitro and in vivo." (PMID 33737929, 2021).